SLC31A1 (solute carrier family 31 member 1)
Diseases named in the same sentence as SLC31A1 in open-access papers (continued):
Sharing a sentence is not in itself a finding about the gene and the disease.
tumor (88 papers, 2015 to 2026). "Overexpression of SLC31A1 was remarkably associated with advanced clinical stage, greater tumor size, and worse overall survival of patients from the two independent OSCC cohorts by immunohistochemistry (IHC)." (PMID 40719074, 2025). "The presence of SLC31A1 in BC is consistent with skewing of the T central memory cell (Tcm) phenotypes, which are associated with anti-tumor response to ICB44." (PMID 39448672, 2024). "In our current study, we systematically described the mRNA and protein expression levels, prognostic value, genetic alterations, molecular function of SLC31A1 in several tumor types as well as the association with immune infiltration." (PMID 36973786, 2023). "According to the results, abnormal SLC31A1 expression was associated with poor prognosis in several tumor types." (PMID 36973786, 2023). "Our results revealed that high expression of the SLC31A1 gene is associated with unfavorable outcomes and an immunosuppressive tumor microenvironment." (PMID 37610668, 2023). "Using ‘CIBERSORT’, we found that SLC31A1 expression was associated with deregulated tumor-infiltrating immune cells." (PMID 35996075, 2022). "In tumor cell-enriched region, higher expression of SLC31A1 (P = 0.001) was associated with worse prognosis of NPC patients, while the opposite was true for LIPT2 (P = 0.012) and ATP7A (P = 0.011)." (PMID 36618352, 2022). "Copper transporter 1 (CTR1, or hCtr1 encoded by SLC31A1), a copper influx transporter, reportedly promotes a significant fraction of cDDP internalization in tumor cells." (PMID 27270317, 2016). "Notably, dysregulation of SLC31A1 showed a strong association with advanced clinical stage, increased tumor size, and poor overall survival." (PMID 40719074, 2025). "Additionally, combining copper chelators with anti‐PD‐1 treatment effectively suppresses tumor growth, and high levels of SLC31A1 are notably associated with non‐response to anti‐PD‐1 treatment." (PMID 40719074, 2025). "In our investigation, SLC31A1 mutations were identified in multiple tumours, including in UCEC." (PMID 37853210, 2023). "A total of 27 SLC31A1 mutations, including 23 missense mutations, one fusion mutation, two frame-shift mutations, and one translation start-codon mutation, were contained in TCGA tumor samples." (PMID 36973786, 2023). "According to the TCGA tumor samples, S105Y is the most prevalent point mutation in SLC31A1." (PMID 36973786, 2023). "While SLC31A1, which encodes the copper importer had a higher expression in tumor tissues." (PMID 36263417, 2022). "Mechanistically, oligodendrocyte-secreted ERBB3 acts as a copper chaperone that competitively mobilizes extracellular copper ions through high-affinity binding to SLC31A1 on tumor cells, thereby promoting intracellular copper accumulation." (PMID 42003929, 2026). "Elevated baseline tumor SLC31A1 expression and post-therapy systemic copper increases converge in high-grade TNBC, indicating a potential coordinated copper mobilization program linked to aggressive biology and neoadjuvant resistance." (PMID 42268797, 2026). "CTR1 (SLC31A1) mediates cellular copper uptake, but its relationship to tumor aggressiveness and neoadjuvant response is unclear." (PMID 42268797, 2026). "We further investigated the relationship between SMURF2 and SLC31A1 expression in tumor tissues from 10 OSCC patients." (PMID 40719074, 2025). "By targeting SLC31A1‐mediated copper influx and EZH2‐driven immunosuppression, our findings support repurposing copper chelators (e.g., TEPA) or developing SLC31A1 inhibitors to disrupt tumor‐intrinsic copper addiction." (PMID 40719074, 2025). "The proliferation, migration, and invasiveness of Her2 + enriched BC cells were decreased by SLC31A1 knockdown, also resulting in a decrease in tumor volume in mouse model." (PMID 39448672, 2024).
tumor (continued). "Afterwards, SLC31A1-knockdown tumors progressively shrank in vivo, showing that SLC31A1, a tumor-promoting factor, significantly downregulated cell proliferation after its knockdown in Her2 + enriched BC cells." (PMID 39448672, 2024). "Conversely, genes like CDKN2A, GLS, MTF1, and SLC31A1 exhibited marked upregulation in the tumor, suggesting distinct roles in the pathophysiology of the disease." (PMID 38898987, 2024). "Patient-derived tumor spheroids exhibited a functional association between autophagy, ID1, SLC31A1, and platinum sensitivity." (PMID 39123206, 2024). "The results showed the relationship between ncRNAs-mediated SLC31A1 and poor prognosis and tumor immune infiltration in BC patients." (PMID 39448672, 2024). "Through the analysis of websites and datasets, Kong and colleagues observed that SLC31A1 expression is elevated in most tumor types, including adrenocortical carcinoma, mesothelioma, and LGG, compared with nontumor tissues." (PMID 38918694, 2024). "Based on TCGA datasets, GEPIA2 was used to investigate the correlation between SLC31A1 expression and prognosis in different tumor types." (PMID 36973786, 2023). "Other genes such as LIPT1, FDX1, and SLC31A1 also play important roles in tumor growth and patient prognosis." (PMID 37239150, 2023). "Our result suggested that the expression of SLC31A1 mRNA was upregulated in 22 tumor types while downregulated in four tumor types compared with the normal tissue." (PMID 37275369, 2023). "In comparison to corresponding normal tissues, the expression of SLC31A1 mRNA was increased in most tumor tissues." (PMID 36973786, 2023). "Our results showed positive correlations of SLC31A1 expression with neutrophil and macrophage infiltration in several tumor types." (PMID 36973786, 2023). "We performed RT-qPCR and found higher SLC31A1 mRNA expression levels in tumour tissues than in normal paratumour tissues." (PMID 37853210, 2023). "Our study further explores the connection between SLC31A1 and tumor immune infiltration to search for more suitable immunotherapy targets." (PMID 37275369, 2023). "For instance, the cuproptosis regulators ATP7B and SLC31A1 are almost exclusively expressed in tumor cells." (PMID 37496994, 2023). "In conclusion, our study showed that the cuproptosis-related gene SLC31A1 plays an essential role in tumour prognosis and immune cell infiltration." (PMID 37853210, 2023). "It was found that tumor samples from UCEC had the highest SLC31A1 genetic alternation frequency (2.46%)." (PMID 36973786, 2023). "The uptake of copper ions by tumor cells also requires the involvement of SLC31A1, which is a major transporter of monovalent copper ions, so that elevated and reduced levels of SLC31A1 expression also directly affect intracellular copper ion levels." (PMID 38131663, 2023). "CBioPortal was then utilized to examine SLC31A1 gene alterations in TCGA datasets of various tumor types." (PMID 36973786, 2023). "GEPIA2 was used to extract the top 100 genes with expression patterns similar to SLC31A1 in all tumor types from TCGA to investigate the gene’s functional impact." (PMID 36973786, 2023). "Overall, we discovered substantial differences in SLC31A1 expression among various tumours with distinct profile types." (PMID 37853210, 2023). "The expression of MTF1, NLRP3, and SLC31A1 was positively related with ImmuneScore, StromalScore, and ESTIMATEScore in almost all types of tumor, whereas ATP7B, DLAT, DLD, LIAS, PDHA1, and PDHB were significantly negatively correlated with the scores." (PMID 36387247, 2022). "We further studied the relative expression of core cuprotosis risk genes NFE2L2, NLRP3, SLC31A1, and GCSH in GC STAD and confirmed that NFE2L2 has low expression in STAD tumor tissue, while SLC31A1 and GCSH genes were highly expressed in STAD tumor tissue." (PMID 36249422, 2022).
tumor (continued). "Among them, 7 genes (DLAT, DLD, GCSH, LIAS, LIPT1, PDHA1, and PDHB) were upmodulated, whereas 3 genes (ATP7B, FDX1, and SLC31A1) were downmodulated in the tumor group in contrast with the normal group (p < 0.05)." (PMID 36046242, 2022). "ATP7B, CDKN2A, FDX1, and SLC31A1 had the lowest expression in tumor cell-enriched region (PanCK-expressing)." (PMID 36618352, 2022). "Consistently, the results showed that DLST and SLC31A1 were expressed differentially between normal tissues and tumor tissues." (PMID 36263417, 2022). "First, SLC31A1 was also important for the uptake of platinum due to its low-affinity, and considered important for tumor response to platinum drugs." (PMID 35996075, 2022). "High expression of SLC31A1 was found to be related with unfavorable outcome and deregulated tumor-infiltrating immune cells." (PMID 35996075, 2022). "The results showed that the level of Slc31a1 mRNA expression was significantly increased in cancer tissues, and its expression was correlated to the copper level in the patient's tumour samples." (PMID 30706544, 2019). "Consistently, Slc31a1 knockout in murine model has also been shown to completely eliminate cisplatin tumor response in vivo." (PMID 29844858, 2018). "However, pan‐cancer analysis showed significant expression differences and prognostic values of SLC31A1 across multiple tumor types based on the TCGA database." (PMID 40719074, 2025). "CTR1 (SLC31A1), the high-affinity copper importer, mediates cellular copper uptake, and its upregulation may signal increased copper demand in tumor cells." (PMID 41480020, 2025). "Studies reveal a close link between cuproptosis-related genes and the tumor microenvironment, where gene expressions such as SLC31A1 correlate with immune cell infiltrates, and high DLAT expression inversely relates to survival in HCC patients with high immune cell infiltration." (PMID 40276654, 2025). "In addition, ROS-responsive nanoparticles loaded with elesclomol and copper ions can serve as a targeted drug delivery system, enabling specific release of the drugs at SLC31A1 highly expressed tumor sites." (PMID 41216190, 2025). "SLC31A1 expression has a substantial link with tumor purity, and it is markedly positively correlated with infiltrating levels of B lymphocytes, CD8 + T cells, CD4 + T cells, macrophages, neutrophils, and dendritic cells in BC, based on the “Gene of TIMER” module study." (PMID 39448672, 2024). "Taken together, these findings suggest that SLC31A1 could present a new target for adjusting Cu balance or cuproptosis in tumor cells." (PMID 38918694, 2024). "Indeed, in pancreatic cancer cells, blocking SLC31A1-dependent copper absorption exacerbates cellular autophagy, leading to the suppression of tumor cell death." (PMID 38918694, 2024). "Patient-derived tumor spheroids were analyzed for autophagy and SLC31A1 levels." (PMID 39123206, 2024). "It has been reported that the suppression of SLC31A1 expression could inhibit tumor growth propelled by the BRAF/MEK/ERK signaling pathway, a classic characteristic of several malignant tumors." (PMID 38918694, 2024). "In contrast, our PPI network results support the hypothesis that SLC31A1 regulates EGFR to promote tumour neovascularisation." (PMID 37853210, 2023). "The expression level of SLC31A1 was positively correlated with tumor immune infiltration." (PMID 37275369, 2023). "In addition, the expression profiles and prognostic values suggest that SLC31A1 functions as a tumour suppressor gene in KIRC." (PMID 37853210, 2023). "Moreover, SLC31A1 expression was positively correlated with the infiltration of immune cells such as macrophages and neutrophils in tumor tissues in several tumor types." (PMID 36973786, 2023). "However, the role of SLC31A1 and its cuproptosis-regulatory functions in multiple tumor types remains to be further elucidated." (PMID 36973786, 2023).
tumor (continued). "SLC31A1 plays an important role in tumour development in immune cells and may serve as a novel biomarker for immune cell infiltration, as indicated by the results presented above." (PMID 37853210, 2023). "As for other tumour types, some immune cells were negatively correlated with SLC31A1 expression." (PMID 37853210, 2023). "We further examined the expression pattern of SLC31A1 in tumor tissues." (PMID 36973786, 2023). "In addition, SLC31A1 also mediates cell uptake of platinum chemotherapy drugs, so previous studies on SLC31A1 mainly focused on tumor drug resistance." (PMID 38085668, 2023). "For each patient, SLC31A1 expression of the tumor sample was higher than that of the normal sample." (PMID 35996075, 2022). "The copper carrier protein 1 (Ctr1; SLC31A1) was initially related to cisplatin due to its increased expression in fungi treated with cisplatin, with further validation from in vitro studies with human tumor cells." (PMID 35682611, 2022). "High levels of SLC31A1 inhibit tumor progression and SLC31A1 blockade promotes tumor development." (PMID 36291668, 2022). "In tumor cell infiltrated areas, higher SLC31A1 expression leads to poorer prognosis of NPC." (PMID 36618352, 2022). "Significant correlation was demonstrated between SLC31A1 and tumor-infiltrating immune cells." (PMID 35996075, 2022). "In addition, both in vitro and in vivo CRISPR/Cas9 screens revealed that CTR1 (Slc31a1) is dispensable for KRAS-mutated cell fitness and tumor growth." (PMID 32709883, 2020). "Additionally, serial monitoring of SLC31A1 levels could aid in early detection of recurrence by reflecting tumor burden changes, complementing traditional imaging techniques." (PMID 41216190, 2025). "The expression of SLC31A1 was positively correlated with immune infiltration, and the single-cell sequencing results indicated that SLC31A1 might be involved in DNA repair, DNA damage and cell proliferation processes in tumor cells." (PMID 39482784, 2024). "Therefore, SLC31A1 may positively regulate B cells, macrophages, and dendritic cells to promote tumor immune escape." (PMID 37275369, 2023). "Notably, increased expression of SLC31A1 in GBM has been associated with reduced patient survival, whereas downregulation of SLC31A1 can impede the proliferation, migration, and invasion of GBM cells, thereby promoting a tumor-suppressive microenvironment." (PMID 38114959, 2023). "Therefore, we inferred that SLC31A1 plays a crucial role in tumour progression." (PMID 37853210, 2023). "Our preliminary findings suggest that SLC31A1 could be involved in a variety of tumor types." (PMID 36973786, 2023). "TRIM21 promotes SLC31A1 expression by enhancing ID1 ubiquitination, thereby inhibiting tumor growth and inducing cuproptosis via the TRIM21‐ID1‐TCF12‐SLC31A1 axis." (PMID 40652518, 2025). "In vivo, EZH2 overexpression significantly increased tumor volumes and weights in xenografts derived from HN6 cells with SLC31A1 knockdown, correlating with increased expression of the proliferation marker Ki67." (PMID 40719074, 2025). "Elevated SLC31A1 expression increases intracellular copper, inducing cuproptosis and inhibiting ESCC cell proliferation and tumor growth." (PMID 40652518, 2025). "Analysis of patient tumor spheroids supported links between elevated autophagy, ID1 and SLC31A1 expression, and platinum sensitivity in clinical samples, thereby validating the relevance of these molecular connections in the highly aggressive HGSOC disease." (PMID 39123206, 2024). "The results revealed that LIAS, DLAT, PDHA1, and CDKN2A were significantly upregulated in LUAD tumors compared to normal tissues, while ATP7B, SLC31A1, FDX1, MTF1, and GLS were significantly downregulated in tumor tissues." (PMID 36983664, 2023).
tumor (continued). "Gene expression profiling showed that SLC31A1, LIPT2, CDKN2A, and GCSH expression was increased in tumor tissues, while NFE2L2, NLRP3, ATP7A, DLD, MTF1, and DLST expression was decreased in tumor tissues compared with normal tissues." (PMID 37065485, 2023). "Nine CRGs were differentially expressed between tumor and normal tissues, among which NFE2L2, SLC31A1, FDX1, DLD, DLAT, and DLST were lowly expressed in tumor tissues, and ATP7B, CDKN2A, and GCSH were highly expressed in tumor tissues (p<0.05)." (PMID 37205181, 2023). "Our study confirmed the overexpression of SLC31A1 in 14 tumours, including CESC, UCEC, and BRCA, and the downregulation of SLC31A1 in nine tumours." (PMID 37853210, 2023). "Consistent with small intestinal epithelial cells, the uptake of copper ions by tumor cells also requires the involvement of CTR1, and the elevated and decreased expression levels of SLC31A1 directly affect intracellular copper ion levels." (PMID 36882769, 2023). "To confirm the expression of SLC31A1 in UCEC, we compared eighteen clinical tissues, including tumour and paratumour tissues, from patients with UCEC." (PMID 37853210, 2023). "SLC31A1 IHC staining is weaker in KIRC and LIHC primary tumour tissues than in normal tissues, but more positive in UCEC than in the normal endometrium." (PMID 37853210, 2023). "In the tumor cell region, the patients with higher expression of LIPT2 and ATP7A had the better prognosis; while the higher the expression of SLC31A1, the worse the prognosis of NPC patients." (PMID 36618352, 2022). "A heatmap showed that the levels of expression of ATP7B, DLAT, DLD, LIAS, and SLC31A1 were upregulated and the levels of expression of DBT, FDX1, and PDHB downregulated in tumor samples." (PMID 36092880, 2022). "Jab1 expression is positively correlated with PDHB (R = 0.37, P = 0.019), DLD (R = 0.37, P = 0.02) and SLC31A1 (R = 0.23, P = 0.15) expression while negatively correlates with DLST (R = -0.32, P = 0.047) expression in tumor cell-enriched region." (PMID 36618352, 2022). "The results showed that, in tumor samples, ATP7B, PDHA1, and SLC31A1 were significantly upregulated compared with normal tissues, whereas ATP7A, DLST, GCSH, LIAS, and LIPT1 were significantly downregulated." (PMID 36567939, 2022). "Cu transporter-related genes including ATP7A, SLC31A1, and TCA-related genes including DBT, DLST, and DLAT are differentially expressed between normal and tumor samples." (PMID 36438201, 2022). "Furthermore, in clinical setting, NSCLC patients with undetectable SLC31A1 expression in their tumors had reduced platinum concentration and tumor response, and lower platinum concentration in clinical specimens correlates directly with reduced tumor response and shorter survival time." (PMID 29844858, 2018). "SLC31A1, a regulatory gene for cuproptosis, has been reported in pan-cancer studies to exhibit higher expression in most tumor types than in non-tumor tissues." (PMID 39482784, 2024). "We then used data from the Tumor Immune Estimation Resource (TIMER) and the Gene Expression Profiling Interactive Analysis (GEPIA) databases to analyze the relationship between SLC31A1 gene expression and immune cell infiltration and the associated gene marker sets." (PMID 37610668, 2023). "The Cancer Genome Atlas (TCGA) datasets showed increased SLC31A1 expression in tumor tissues compared with non-tumor tissues in most tumor types." (PMID 36973786, 2023). "Based on the analysis of scRNA-seq, the expression of FDX1, DLD and SLC31A1 was much higher in non-tumor tissues than those in tumor tissues, consistent with our findings from a bulk sequencing analysis." (PMID 36733399, 2022). "The other five CRGs, including FDX1, SLC31A1, LIPT2, PDHA1 and GCSH, did not have any mutations in tumor samples." (PMID 36479114, 2022).
tumor (continued). "Analysis of clinicopathological features revealed that elevated SLC31A1 expression significantly correlated with poor differentiation, advanced TNM stage, extrathyroidal extension, and lymph node involvement, suggesting its role in tumor aggressiveness and metastatic potential." (PMID 41216190, 2025). "FDX1, LIAS, LIPTQ, SLC31A1, and PDHB showed no mutation in LUAD tumor tissues." (PMID 36983664, 2023). "Additionally, other copper chaperones, such as SCO1 (Synthesis of Cytochrome C Oxidase 1), SLC31A1 (Solute Carrier Family 31 Member 1), and COX11 (Cytochrome C Oxidase Copper Chaperone), may contribute to increased copper influx into the tumor, which is necessary for CRC growth." (PMID 39518128, 2024).